TRPC6 (transient receptor potential cation channel subfamily C member 6)
Diseases named in the same sentence as TRPC6 in open-access papers (continued):
Sharing a sentence is not in itself a finding about the gene and the disease.
chronic kidney disease (10 papers, 2013 to 2025). Impairment of the renal function secondary to chronic kidney damage persisting for three or more months. "Another study has suggested that activation of TRPC6 channels is linked to renal injury and may contribute to the development of chronic kidney disease in STZ-induced type 1 diabetic Dahl salt-sensitive rats." (PMID 34866402, 2022). "Although genotype-phenotype correlation of this novel TRPC6 mutation is not known, all three affected adults presented with proteinuria at 32–34 years of age, with progressive chronic kidney disease subsequently developing in the proband’s mother and brother." (PMID 23663351, 2013).
nephrosis (10 papers, 2018 to 2023). Pathological processes of the KIDNEY without inflammatory or neoplastic components. "Over a decade ago, mutations in the gene encoding TRPC6 (transient receptor potential cation channel, subfamily C, member 6) were linked to development of familial forms of nephrosis." (PMID 31877991, 2019). "Other mutations in TRPC6 that lead to nephrosis have been identified." (PMID 33520986, 2020). "However, relatively few non-syndromic, genetic causes of nephrosis had been reported in the year (2005) that mutations in TRPC6 were linked to the development of autosomal dominant FSGS." (PMID 31877991, 2019). "In line with the central role of TRPC6 in cytoskeletal rearrangements during podocyte injury, podocyte-specific TRPC6 expression is indeed increased during PAN-nephrosis." (PMID 38003608, 2023). "In the animal model of puromycin aminonucleoside nephrosis, oxidative stress and the increased activation of TRPC6 are well established." (PMID 36429053, 2022). "Here we have examined if TRPC6 channels play a role in the progression of chronic puromycin aminonucleoside (PAN) nephrosis in rats, an extensively studied model of severe secondary FSGS." (PMID 29785489, 2018). "Here we examined a possible role for TRPC6 in the progression of chronic puromycin aminonucleoside (PAN) nephrosis in Sprague-Dawley rats, a classic model of acquired nephrotic syndromes." (PMID 29785489, 2018). "Also importantly, TRPC6 inactivation using CRISPR/Cas9 resulted in a reduced glomerular influx of macrophages as compared to WT littermates upon PAN-induced nephrosis." (PMID 38003608, 2023). "Moreover, a systemic TRPC6 knockout during PAN-induced nephrosis resulted in reduced tubulointerstitial fibrosis, tubulointerstitial inflammation and tubular injury." (PMID 38003608, 2023). "Studies in multiple strains of mice and rats with global knockouts or complete loss of TRPC6 function also exhibit no signs of nephrosis, even in old age." (PMID 37615749, 2023). "Many molecules, including TRPC6 channels, are associated with PAN-induced nephrosis in rats." (PMID 34621762, 2021). "In addition, it has been found that TRPC6 inactivation or inhibition is involved in the protective role of severe nephrosis." (PMID 33520986, 2020). "On the other hand, deletion of TRPC6 channels confers renoprotection in a model of nephrosis." (PMID 31950205, 2020). "TRPC6 inhibition improves protein retention in rat models of nephrosis, suggesting that aberrant TRPC6 function might also exacerbate the clinical picture of patients with acquired forms of glomerular injury." (PMID 29973568, 2018). "Moreover, the TRPC6 knockout decreases proteinuria during PAN-nephrosis." (PMID 38003608, 2023). "As PAN-induced nephrosis is a glomerular injury model, reduced tubulointerstitial fibrosis could be a secondary result of reduced glomerular injury, decreased proteinuria and tubular protein overload after TRPC6 KO." (PMID 38003608, 2023).
Stroke (10 papers, 2019 to 2025). Sudden impairment of blood flow to a part of the brain due to occlusion or rupture of an artery to the brain. "Evidence has shown that TRPC6 is involved in the process of experimental stroke; however, the underlying mechanisms remain unclear." (PMID 33604333, 2020). "Furthermore, the protective role of TRPC6 in stroke is associated with Ca2+/NF-κB-dependent pathways." (PMID 33604333, 2020). "Abnormal TRPC6 function is detrimental to neurons after stroke, given that Ca2+ overload contributes to cell death following ischemia." (PMID 36527242, 2023). "Accumulated evidence has confirmed the beneficial role of TRPC6 post‐stroke using hyperforin, resveratrol, peanuts, (‐)‐epigallocatechin‐3‐gallate, calycosin, monoterpene oxide 1,8‐cineole (cineole), and tetramethylpyrazine." (PMID 36527242, 2023). "Appropriate TRPC6 protein levels for post‐stroke neuroprotection are also maintained by the cyclic AMP response‐element binding protein (CREB) signaling pathway." (PMID 36527242, 2023). "To date, the important role of TRPC6 protein has been identified in studies of many neurological disorders such as stroke, ASD and epilepsy, suggesting the importance of TRPC6 in maintaining normal neuronal function." (PMID 34327201, 2021). "In conclusion, the results show that application of the TRPC6 agonist HYP9 can alleviate IR-induced cerebral injury in an animal model of stroke." (PMID 33604333, 2020). "Recent studies have shown that suppression of TRPC6 channel degradation prevents ischemic neuronal cell death in experimental stroke." (PMID 32256338, 2020). "Overexpression of TRPC6 also reduced IR injury-induced astrocytic apoptosis, cytotoxicity, and inflammatory responses in experimental stroke in vitro." (PMID 33604333, 2020). "Overall, further in vivo studies using astrocytic TRPC6-, siRNA-, or shRNA-targeted transgenic mice are needed to fully clarify the role of the astrocytic TRPC6 channel in stroke." (PMID 33604333, 2020). "Further, we also found that TRPC6 expression elevated in both stroke-induced rat podocytes and human podocytes exposed to FG-4592." (PMID 31784544, 2019). "Immunostaining data revealed that increased expression of HIF1α, ZEB2, and TRPC6 in glomeruli from stroke-induced rats." (PMID 31784544, 2019). "Similarly, neuroprotection in a rat stroke model was observed via TRPC6/CREB using “Neuroprotectin D1” when applied after reperfusion." (PMID 33669830, 2021). "Additionally, TRPC6 also holds important roles in stroke therapy, which will be discussed in further detail below." (PMID 32256338, 2020). "Besides, the primary goal is to discuss and update the critical role of TRPC6 channels in stroke and provide a promising target for stroke prevention and therapy." (PMID 32256338, 2020). "Collectively, the findings indicate that NF-κB phosphorylation and nuclear translocation may be pivotal downstream pathways that contribute to the protective effects of TRPC6 in astrocytes after stroke." (PMID 33604333, 2020). "In brain, TRPC6 expression was reduced in a rat model of stroke." (PMID 33135341, 2020). "Therefore, TRPC6 degradation after stroke is calcium dependent." (PMID 36527242, 2023). "In addition, we provide a novel view of stroke therapy by targeting the astrocytic TRPC6 channel." (PMID 33604333, 2020). "In the present study, the role of astrocytic TRPC6 was investigated in an oxygen–glucose deprivation cell model and middle cerebral artery occlusion (MCAO) mouse model of stroke." (PMID 33604333, 2020). "Overall our results establish that TRPC6 is a novel target of HIF1α/ZEB2 axis and that transduces stroke-induced ischemia-hypoxia injury in podocytes." (PMID 31784544, 2019). "Resveratrol, neuroprotectin D1, and the main compound of green tea, (−)-epigallocatechin-3-gallate, inhibit calpain-mediated TRPC6 proteolysis and activate MEK/ERK or CaMKIV-dependent CREB pathways, therefore improving neurological status in experimental stroke." (PMID 32256338, 2020).
ischemic stroke (9 papers, 2017 to 2025). A stroke disorder caused by obstruction of blood flow to the brain, due to thrombotic (local blood clot formation) or embolic (due to a blood clot or other material traveling from another site) event. "Furthermore, a TRPC6 activator was found to ameliorate neuronal death in ischemic stroke and this was associated with improved phosphorylated CREB (p-CREB) activity." (PMID 33669830, 2021). "Paradoxically one family member, TRPC6, has been linked to neuroprotection with ischemic stroke." (PMID 33669830, 2021). "Consequently, HYP9 was used in the present study to explore its function in the TRPC6 channel and the associated downstream cellular mechanisms in ischemic stroke." (PMID 33604333, 2020). "Furthermore, the underlying mechanisms of TRPC6-triggered astrocytic Ca2+ changes in ischemic stroke warrant further investigations." (PMID 33604333, 2020). "Furthermore, overexpression of TRPC6 in BMSCs improves neuronal functions in rats after ischemic stroke, which is associated with BDNF/CREB pathway." (PMID 32256338, 2020). "Interestingly, an imbalance in TRPC6 expression (too much or too little) may be associated with neuronal death in ischemic stroke." (PMID 33669830, 2021). "Increased TRPC6 expression is observed in the cortical neurons after OGD/R, and Trpc6 knockout protects mice against ischemic stroke." (PMID 41399206, 2025). "In fact, TRPC6 protein degradation was originally reported in the context of ischemic stroke via calpain-mediated proteolysis involving the calpain cleavage of the N-terminal domain of TRPC6 at Lys16." (PMID 40498020, 2025). "Enhanced TRPC6 expression suppressed NMDA receptor-mediated Ca2+ neurotoxicity, and several molecular probes modulated brain function and promoted neuroprotection and recovery in ischemic stroke by enhancing TRPC6 channel function." (PMID 33669830, 2021). "Alterations in TRPC6 activity following ischemic stroke is likely to alter intracellular Ca2+, that modulates NMDA receptor activity or affects the release of vasoactive mediators, such as nitric oxide (NO) and AA derivatives." (PMID 33669830, 2021). "This review discusses evidence-based cell-specific aspects of TRPC6 in the brain to assess the potential targets for ischemic stroke management." (PMID 33669830, 2021). "During the process of ischemic stroke, increasing evidences support that TRPC6 seems to be a protective pathway." (PMID 32256338, 2020). "In the present study, the specific effects of astrocytic TRPC6 on ischemic stroke were investigated." (PMID 33604333, 2020). "We have highlighted some crucial advancement that points toward an important involvement of TRPCs and TRPC6 in ischemic stroke." (PMID 32256338, 2020). "In contrast to the rich information on TRPC6, little is known about the roles of TRPC4 and TRPC5 in brain injury associated with ischemic stroke." (PMID 33490083, 2020). "The primary aim is to clarify the relationship between TRPC6 and ischemic stroke and discuss future perspectives." (PMID 32256338, 2020). "HYP9 (a selective TRPC6 agonist) and SKF96365 (SKF; a TRPC antagonist) were used to clarify the exact functions of TRPC6 in astrocytes after ischemic stroke." (PMID 33604333, 2020). "Due to that fact, TRPC6 has emerged as an alternative therapeutic target for AD and ischemic stroke." (PMID 33114455, 2020). "In a rat model of ischemic stroke, NPD1 administration is associated with a significantly elevated TRPC6 and CREB activity, while the inhibition of the MEK/ERK pathway results in a decrease in NPD1 neuroprotective activity." (PMID 33114455, 2020). "In contrast to previous studies, TRPC6 expression was proved to be increased in wild-type mice neurons after ischemic stroke." (PMID 32256338, 2020). "Recently, growing evidence indicates that TRPC6 channel has been involved in Ca2+ homeostasis and shown to participate in the molecular pathophysiology of ischemic stroke." (PMID 32256338, 2020).
ischemic stroke (continued). "Particularly, the TRPC6 activator, hyperforin, also contributes to neuroprotection after ischemic stroke by blocking TRPC6 degradation accompanied by elevation of phosphorylated CREB in CaMKIV and Ras/MEK/ERK-dependent mechanisms." (PMID 32256338, 2020). "TRPC6 was reported to have an critical role in neuroprotection in both in vitro and in vivo models of ischemic stroke." (PMID 32256338, 2020). "However, TRPC6 activation reduces IL‐1β and IL‐6 release and NF‐κB activity in an in vitro ischemic stroke model, partly via inhibiting Ca2+ signaling." (PMID 41399206, 2025). "TRPC6 generally confers a neuroprotective role in ischemic stroke by preventing neuronal death." (PMID 41399206, 2025). "High ROS levels also may activate plasma membrane proteins (such as TRPC6) that are important in ischemic stroke, a condition where hypoxia plays a significant role." (PMID 35053996, 2022). "The latest research shows potential for new TRPC6 agonists and antagonists in preclinical experiments, specifically related to neuroscience, which may have a useful role in ischemic stroke in the future." (PMID 33669830, 2021). "Here, we assess the evidence for and against the beneficial consequence of TRPC6 activation in ischemic stroke, its cell-specific roles in the brain, what is known about the involvement of TRPC6 in neurovascular coupling, and the potential therapeutic options for targeting TRPC6." (PMID 33669830, 2021). "Thus, many factors should be thoroughly considered before studies are conducted to explore the effect TRPC6 on ischemic stroke." (PMID 32256338, 2020). "The results of this study indicate that the astrocytic TRPC6 channel and TRPC6 agonist HYP9 might be a novel therapeutic approach to prevent ischemic stroke induced by brain injury." (PMID 33604333, 2020). "The evidence discussed here indicates that compounds targeting TRPC6 may have clinical potential as novel agents for prevention and treatment of ischemic stroke." (PMID 32256338, 2020). "Furthermore, this study provides therapeutic evidence for the treatment of ischemic stroke by targeting the TRPC6 channel." (PMID 33604333, 2020). "Collectively, these evidences suggest the vital role of TRPC6/CREB pathway in ischemic stroke." (PMID 33604333, 2020). "Consequently, to determine the role of TRPC6 in an in vivo model of ischemic stroke, intraventricular administration of HYP9 or SKF was performed in mice." (PMID 33604333, 2020). "Since TRPC6 channels are permeable to Na+ and Ca2+, we hypothesized that ischemic stroke and OGD may increase TRPC6 expression which may, in turn, activate NMDA receptors (NMDAR) and enhance Ca2+ influx." (PMID 28400714, 2017). "However, studies demonstrated a detrimental effect of TRPC6 in ischemic stroke." (PMID 41399206, 2025). "Increased degradation of TRPC6 after ischemic stroke may result in neuronal damage." (PMID 33669830, 2021). "We believe that the TRPC6-CaMKIV-CREB pathway may be an important mechanism of ischemic stroke." (PMID 32256338, 2020). "As noted, the combination treatment of oxiracetam and bone marrow stromal cells increases TRPC6 and p-CREB levels and protects from neuronal death in ischemic stroke." (PMID 33669830, 2021). "Further research is needed to establish what role, if any, TRPC6 plays in endothelial function and BBB integrity in ischemic stroke." (PMID 33669830, 2021). "The maintenance of TRPC6 expression via CREB-dependent mechanisms has a neuroprotective effect, and has potential as a protective strategy against ischemic stroke." (PMID 32256338, 2020).
type 1 diabetes (9 papers, 2019 to 2023). "Thus, type 1 diabetes induced by STZ is associated with increased glomerular TRPC6 expression in Dahl SS rats." (PMID 36421724, 2022). "The higher Ang II-mediated Ca2+ response accompanied by increase in TRPC6 expression was observed earlier in type 1 diabetes." (PMID 37108424, 2023). "In one experimental model of type 1 diabetes performed on Akita mice, TRPC6 KO resulted in increased insulin resistance and subsequently caused increased glomerular injury and disease progression." (PMID 38003608, 2023). "A similar controversial role of TRPC6-mediated Ca2+ entry in the context of immune-related glomerular diseases has been described for type 1 diabetes." (PMID 38003608, 2023). "Knockout of TRPC6 in type I diabetic mice promoted insulin resistance, and TRPC3 knockdown resulted in a decreased insulin-mediated glucose uptake in adult skeletal muscle cells." (PMID 32872338, 2020). "For example, a protective effect of Trpc6 knockout was observed in the Akita mouse model of type 1 diabetes at 12 and 16 weeks of age." (PMID 32123821, 2019). "TRPC6 knockout or downregulation in podocytes was protective in several models of diabetes type 1." (PMID 37108424, 2023). "Finally, in the streptozotocin model of type 1 diabetes, we saw no protective effects of global TRPC6 inactivation anywhere in the kidney." (PMID 33918778, 2021).
Ureteral obstruction (9 papers, 2018 to 2025). Obstruction of the flow of urine through the ureter. "While significant protective effects in the interstitium were not evident in the present study, is now well established that TRPC6 knockout in mice reduces tubulointerstitial fibrosis evoked by unilateral ureteral obstruction (UUO)." (PMID 35805070, 2022). "In the kidney, both genetic, and pharmacologic, inhibition of TRPC6 is reported to dampen the fibrotic response in the unilateral ureteral obstruction model." (PMID 35913909, 2022). "TRPC6 knockout in mice resulted in marked reductions in tubulointerstitial fibrosis observed after unilateral ureteral obstruction." (PMID 35805070, 2022). "TRPC6 knockout in mice reduces tubulointerstitial fibrosis following ureteral obstruction, and soluble klotho appears to exert part of its protective effects in vivo by suppressing TRPC6 expression in the kidney." (PMID 33918778, 2021). "In this study, TRPC6−/− and wild-type (WT) mice were subjected to a unilateral ureteric obstruction (UUO) operation." (PMID 33520986, 2020). "TRPC6 channels also contribute to fibroblast activation in kidney following unilateral ureteral obstruction in mice." (PMID 29785489, 2018). "In the current study, we found that TRPC6 knockout could alleviate kidney tubulointerstitial fibrosis mediated by EMT after unilateral ureteric obstruction (UUO) in vivo." (PMID 33520986, 2020). "Likewise, TRPC6 knockout has been shown to have protective effects in mouse models in which tubulointerstitial disease is followed from an initial insult to tubules as a result of unilateral ureteral obstruction (UUO)." (PMID 37615749, 2023). "Alternatively, TRPC6-dependent fibrosis pathways may be activated specifically downstream of ureteral obstruction, and not involved in the models tested here." (PMID 35913909, 2022).